CXCL10 (C-X-C motif chemokine ligand 10)
Diseases named in the same sentence as CXCL10 in open-access papers (continued):
Sharing a sentence is not in itself a finding about the gene and the disease.
tumor (continued). "Therefore, we stained tumor sections for Cxcl9 and Cxcl10 from untreated KPC2a-bearing mice and mice treated with αPD-L1 or CD40 agonist as such therapies may enhance IFNγ, which induces Cxcl9/Cxcl10." (PMID 36472588, 2023). "Moreover, using multiple HCC preclinical models and an ex vivo tumor fragment platform, we dissect the mechanisms by which LDRT sensitizes DPVB by enlarging intratumoral stem-like CD8+ Tpex, which are recruited from the draining lymph nodes (dLNs) into the tumor through the CXCL10/CXCR3 axis." (PMID 38001101, 2023). "In addition, accumulating evidence has suggested that the CXCL10 and CXCL11/CXCR3 axis could impose antitumor effects by recruiting Th1 cells, cytotoxic T cells, natural killer cells, and natural killer T cells to tumor sites and it has protumor effects on cancer cells expressing CXCR3." (PMID 36003333, 2022). "In addition to their roles in tumor growth, some of these mediators may also play important roles in the development of neuropathic pain, e.g., complement 5 (C5), or the CXCR3 receptor, and its ligand CXCL10." (PMID 35962398, 2022). "Furthermore, CCR5-CCL4/CCL5 and CXCR3- CXCL9/CXCL10/CXCL11/CXCL13 axis were significantly correlated with CD 4 T and CD 8 T cells, indicating that these interactions may be essential for the recruitment of the T lymphocytes into tumor." (PMID 35530341, 2022). "Moreover, as DC-reprogrammed tumor cells could promote the recruitment of T-cells to the tumor site by the secretion of CXCL9 and CXCL10, such strategy could also potentiate the effect of other T-cell-based cancer immunotherapies including immune checkpoint blockade and adoptive cell transfer." (PMID 34367185, 2021). "Likewise, tumor with low CXCL10 expression displayed a general lack of immune infiltration." (PMID 34386037, 2021). "Moreover, CXCL10, CXCL12, and CCL7, which may promote tumor progression, were also highly induced." (PMID 34771453, 2021). "In addition, CXCL10 could, through its receptor CXCR3, induce the mobilization, differentiation and angiogenesis of endothelial progenitor cell (EPC), which resulted in progressive tumor growth." (PMID 34360975, 2021). "However, it was observed that the cytokines CXCL10 and IFN-γ specifically showed elevated levels in the tumor tissues over 24 and 48 h which could imply that these cytokines play an important role in eliciting an anti-tumor immune response." (PMID 34575506, 2021). "Having established that IFN-γ increases MHC Class I expression and induces CXCL10 secretion from SCC cells in vitro, we next examined whether IFN-γ may play a role in modulating MHC Class I expression in vivo and initiating the infiltration of T cells into tumours." (PMID 33925140, 2021). "Sirt1 could enhance the tumor killing ability of macrophages, and deacetylate K310 of the p65 subunit in NF-κB, thereby increasing the infiltration of CD8+T cells in tumors or increasing the expression of CXCL10, so as to recruit NK cells and macrophages into tumor microenvironments." (PMID 34880761, 2021). "Lack of Ccl2, Ccl5, and Cxcl10 expression in 4T1ρ0 cells posed the question of whether or not macrophage recruitment into 4T1ρ0 tumors early in their development was compromised, and if so, whether or not this affected tumor formation." (PMID 33329014, 2020). "However, the average expression of CXCL10 and CXCL9 was higher in Group 2 tumors by 22.8-fold and 12.3-fold, respectively, which supports the idea that Group 2 tumors were “immune-active”, which may have resulted in a PD-1 positive tumor immune environment." (PMID 31618954, 2019). "The expression of the CXCL9 and CXCL10 chemokines, together with HLA class II, OX40L, and PD-L2 are suggestive of the presence of antigen-presenting cells in the microenvironment while TIM-3 expression may reflect an activated/dysfunctional phenotype of tumor-infiltrating T cells." (PMID 31888734, 2019).
tumor (continued). "Therefore, it might not be surprising that genes such as GZMB and CXCL10, which are expressed by non-cancerous cells, were among top ones predicted to be induced by intra-tumor microbiota." (PMID 30294508, 2018). "Still since CXCL10 is known to play a critical role in attracting T cells into the tumor microenvironment and is under the control of type I IFN, it seems reasonable to speculate that the IFNβ transgene modulates the chemokine milieu to recruit immune effectors into the tumor microenvironment." (PMID 28536345, 2017). "According to the strong signal for CXCL10 in transformed epithelial cells, it is possible that attraction of CXCR3+ Th1 cells by transformed epithelial cells may enhance IFN-dependent production of COX2 in tumor areas, enhancing local tumor angiogenesis and immunosuppression." (PMID 28567040, 2017). "Pathways involving tumor-expressed extracellular membrane-bound chemokines CXCL9, CXCL10, and CXCL11 were identified and show potential interactions in networks translating intracellular damage to extracellular signals that may stimulate immune recruitment and tumor cell death." (PMID 25952672, 2015). "Thus, CD4+ T cells may also mediate upregulated expression of angiostatic chemokines such as CXCL9, CXCL10, and CXCL14 that are capable of inhibiting tumor growth or may downregulate expression of the chemokine receptor CXCR2 or its many ligands that promote angiogenesis." (PMID 26618181, 2015). "In terms of therapeutic efficacy, no tumour remission was observed in mice bearing L1CAM-low (SK-N-AS) tumours, regardless of CXCL10 expression." (PMID 41366257, 2025). "Depletion of Ptdss1 in tumor cells increased expression of interferon-γ (IFN-γ)–regulated genes, including B2m, Cxcl9, Cxcl10, and Stat1, even in the absence of IFN-γ stimulation in vitro." (PMID 40929270, 2025). "Last, but not least, there is growing evidence that CXCL9/CXCL10/CXCR3 and CXCL16/CXCR6 are involved in tumor pathogenesis, so they probably represent pleiotropic chemokines at the crossroads of immunity and carcinogenesis." (PMID 41373861, 2025). "A recent study in a murine melanoma model demonstrated a failure in the trafficking of CAR-T cells in the tumor due to the absence of T-cell trafficking signals CXCL9 and CXCL10, produced by DCs." (PMID 38785789, 2024). "Neurons in the TME release CXCL10, which interacts with CXCR3 on Nonneurogenic tumor cells, activating downstream pathways (Akt, MEK, RAC) that facilitate tumor infiltration into peripheral nervous tissues." (PMID 39429695, 2024). "The results of the P815-IFNG tumor models displayed a significant increase in the transcriptional or translational levels of murine IFNG and CXCL10 in the light group, rather than IL-6 or IL-10." (PMID 39080467, 2024). "CCL5 was found to be remarkably elevated in tumor tissues collected from PTC patients coexistent with HT than those without HT, and CXCL9, CXCL10, CXCL11, and CXCL13 were also reportedly upregulated in thyroid tissues from HT patients." (PMID 38137348, 2023). "Interferon (IFN)-inducible chemokines C-X-C motif ligand 9 (CXCL), CXCL10, and CXCL11 are anti-tumor chemokines; however, the differential anti-tumor effects of IFN-inducible chemokines are not completely understood." (PMID 37218983, 2023). "Conversely, ARID1A, a core member of the SWItch/Sucrose Non-Fermentable (SWI/SNF) complex, promotes tumor expression of CXCL9 and CXCL10." (PMID 36600243, 2023). "CCL5 regulates the expression of CXCL9 (but not CXCL10) in the TAMs, thus allowing the recruitment of CD8 T cells within the tumor and tumor growth control." (PMID 36429101, 2022). "We further found that tumor-rich tissues produced higher levels of CXCL9, CXCL10 and CXCL11 compared to nontumor tissues." (PMID 35954489, 2022).
tumor (continued). "Similar observations were made when only the ccRCC cases were included; significant positive correlations were observed for both CXCL10 and CXCL9 with the tumor lymphocytes and CD3 + T cells, respectively, but not with the NK cells (Supplementary S5Bi-vi)." (PMID 35927313, 2022). "Whereas the addition of Cxcl10 WT sensitized CT26-Nanog tumors to PD-1 blockade and accelerated overall CD8+ T cell or tumor-reactive CD8+ cell recruitment, Cxcl10 MT had no impact on these parameters." (PMID 35104240, 2022). "Next, we set out to characterize the relevance of CXCL10 for the fibrotic non-tumorigenic microenvironment and the tumor stroma composition during hepatic carcinogenesis using HCC- bearing WT and Cxcl10−/− mice." (PMID 35897689, 2022). "Collectively, a negative correlation between CXCL10 and CD8+ T cell infiltration was observed in the tumor tissues." (PMID 35259052, 2022). "We found that the secretion of CXCL9, CXCL10 and CXCL11 was significantly higher in central tumor tissues compared to nontumor tissues." (PMID 35954489, 2022). "On the contrary, CXCL4, CXCL9, CXCL10, CXCL11, CXCL12, CXCL13, and CXCL14, lacking the ELR amino acid motif (ELR−), can inhibit tumor angiogenesis." (PMID 34497764, 2021). "Only VEGF was more expressed by CD49a+Eomes+ cells in nontumorous liver tissue, while in the tumor, CD49a+Eomes+ cells expressed higher levels of VEGF, PlGF, IL-8, MMP-9, angiogenin, and CXCL10 (IP-10)." (PMID 33802077, 2021). "The cGAS-STING pathway was not activated in MB49 in the presence of dsDNA, but responded to direct stimulus of cGAMP producing CXCL10 and expressing IFN-β, which suggests that cGAS is not active in this tumor cell line." (PMID 34341449, 2021). "In our model, mice treated with an antibody to block the binding of CXCL10 and CXCL11 to CXCR3 (but not the binding of CXCL9 to CXCR3) were unable to control the growth of established tumours." (PMID 33925140, 2021). "In triple-negative BRCA, CXCL10 and CXCR3 were shown to contribute to tumor invasiveness and metastasis in spite of a high density of T cell infiltrate." (PMID 34067089, 2021). "Compared with TC-1 without irradiation, TC-1 tumor cells pretreated with irradiation were induced greater production of CCL5 and CXCL10 by IFN-γ." (PMID 33469123, 2021). "Cytokine analysis in tumor patients revealed comparatively lower levels in IL-16, IL-18, CXCL8 (IL-8), IL-9, and CXCL10 (IP-10), indicating that the higher T cell numbers were not accompanied by increased T cell activity." (PMID 30740106, 2019). "This occurred without implication of intratumoral chemokine expression because RNA‐seq analysis did not reveal reduced mRNA levels for CXCL‐9, CXCL‐10, and CXCL‐11 in bulk tumor tissue of male STAT1∆IEC mice (data not shown)." (PMID 29419930, 2018). "For example, the tumor supernatants contained low levels of CXCL9, CXCL10 and CXCL11 (data not shown) that bind to CXCR3, a chemokine receptor known to be upregulated on NK cells upon activation and expansion." (PMID 28923105, 2017). "As for the murine cells, the chemotactic responses towards various concentrations of chemokines were tested and confirmed the migratory ability of the human tumour cells in response to two of the three ligands (CXCL9, CXCL10 but not CXCL11)." (PMID 19436305, 2009). "Functional validation via in vitro chemotaxis assays and in vivo xenograft models demonstrates that CXCL10 overexpression suppresses tumor growth by enhancing effector immune cell infiltration, while CCL20 promotes Treg accumulation without impeding tumor progression." (PMID 41399390, 2026). "IFN-γ can induce tumor cell death and trigger the release of a large number of cytokines, such as CXCL9, CXCL10, and CXCL11, thereby further recruiting NK cells and macrophages to the tumor microenvironment and inducing a non-specific anti-tumor immune response." (PMID 38534538, 2024).
tumor (continued). "However, a number of tumor types, including prostate cancer, did not express CXCL9 and CXCL10, which prevented CD8+ effector T cells from activating." (PMID 37546397, 2023). "In stromal-rich regions that lacked CK + tumor cells, 1045 T cells + CD40 agonist increased Cxcl9/Cxcl10 expression by macrophage and 1045 T cells appeared to colocalize with the Cxcl9 + macrophage in these stromal regions, similar to our results in resected human PDA." (PMID 36472588, 2023). "On the basis of the principle of ceRNA hypothesis, C22orf34, RFPL1S, and LINC00996 shared same expression patterns as CXCL10, CXCL9, CCL5, FCGR3A, and CCR2, all which were upregulated in tumor tissues of PTC with HT compared with those without HT." (PMID 36266640, 2022). "Therefore, CXCL9, CXCL10, and CXCL11 have crucial, nonredundant, cell-autonomous roles mediating immune cell infiltration into tumors, and inducing effective anti-tumor immunity." (PMID 35493527, 2022). "Since CXCL9 and CXCL10 are IFN-γ–inducible chemokines, lack of IFN-γ secretion by immune cells in the tumor could lead to a negative feedback loop, preventing further CD8 T cell recruitment." (PMID 35103755, 2022). "However, only STINGR284S mRNA, not STINGWT mRNA, stimulated the production of anti-tumor cytokines, such as CCL5, CXCL10, IL29, IL6, IFNβ and TNFα." (PMID 36498833, 2022). "In contrast to Brca2WT tumours, we did not observe a further increase in the number of CD3+ or CD8+ T cells upon Cxcl9 overexpression in the Brca2−/− model, possibly as a result of a saturation effect by the elevated STING-dependent chemokines, e.g. Cxcl10." (PMID 35314795, 2022). "The fact that CXCL10 expression does not differ between the DCIS and invasive components of the same tumor may represent early alteration of gene expression." (PMID 34504204, 2021). "While DOX administration in tumor-free mice did not result in significant changes in the expression of inflammatory markers in the heart, DOX administration significantly abrogated the tumor-induced upregulation of IL-1β, Mcp-1, Cxcl9, and Cxcl10." (PMID 34445729, 2021). "However, CXCL10 mRNA expression was not statistically different between DCIS and invasive components of the same tumor in the whole group, and HR-positive and HR-negative subgroups (p = 0.710, p = 0.754 and p = 0.875, respectively)." (PMID 34504204, 2021). "In colorectal cancer, the lack of METTL3 or METTL14 increases cytotoxic tumor-infiltrating CD8+ T cells; enhances the production of interferon- (IFN-) γ, CXCL9, and CXCL10; and promotes the recruitment of CD8+ and CD4+ effector T cells that inhibit tumor growth." (PMID 34858499, 2021). "Changes in tumor-associated lymphocytes (e.g., CD3+, CD4+, and CD8+), upregulation of INF-gamma stimulated genes in tumor transcripts, and increase in chemokines (e.g., CXCL9 and CXCL10) were observed, while no significant change in PD-L1 expression under nivolumab treatment was reported." (PMID 32630154, 2020). "This drastic change of NK cell number was not attributable to changes of CXCR4 and CXCR3 ligand expression levels since CXCL10 expression in the BM was not modulated by NK cell transfer or IL-15 administration, nor was the expression of CXCL10 and CXCL12 by BM tumor cells." (PMID 31699153, 2019). "It was later found that in a tumor model resembling non-T cell-inflamed human tumors, adoptive transferred T cells failed to traffic into tumor site due to the absence of CD103+ DC secreting CXCL9 and CXCL10." (PMID 30064449, 2018). "Accordingly, we analyse the cytokine expression changes (more than 1.5 log2, 2.8 fold, p < 0.05, t-test) between No take and Take tumours and found a large series of chemokine/cytokine overexpressed in the No take samples, among them IFNG, CXCL13, CXCl9, CXCl11, CXCL10 and CCL5." (PMID 28588211, 2017).
tumor (continued). "Also, levels of the three chemokines CXCL9, CXCL10 and CXCL11 were markedly higher, exclusively in Lebanese tumor tissue as compared to non-tumor breast tissue, making BC in this population prone to metastasis." (PMID 27857161, 2016). "Similar to tumor tissues, CXCL9 protein levels were substantially increased in sera of mice in the combination group, although no CXCL10 could be detected." (PMID 28123870, 2016). "CXCL10 production by CD103+ cDC1s was shown to be required for endogenous and adoptively transferred effector T cells migration into tumor sites, suggesting that the absence of intratumoral cDC1s may contribute to tumor immune escape mechanisms and limited responses to ICB." (PMID 37830618, 2023). "Tumors with brisk/non-brisk tumor-infiltrating lymphocytes (TIL) vs. absence of TIL exhibited significantly higher levels of APRIL/TNFSF13 (p = 0.01), CCL19 (p = 0.01) and CXCL13 (p = 0.01), but no such difference was observed for patients’ serum levels of CXCL10 (p = 0.97)." (PMID 37435077, 2023). "However, we found that autophagy inhibition by CQ or ULK1 depletion did not increase the expression of CCL5 or CXCL10 in NSCLC cells, suggesting that autophagy inhibition could not promote the infiltration of NK cells into NSCLC tumor." (PMID 35002511, 2022). "CXCL10 does not have the structural domain ELR “Glu-Leu-Arg” tripeptide motif, which is present in certain CXC chemokines and which might have anti-angiogenic along with anti-tumor properties." (PMID 36366543, 2022). "Furthermore, in keeping with the effect of EZH2 inhibition in tumor cells, Mo-TAMs from EPZ-6438-treated MCS showed a consistent enhanced expression of monocyte chemoattractants CCL2 and VEGF but not Th1-recruiting chemokines (CXCL9, CXCL10, CXCL11)." (PMID 33922336, 2021). "Through analysis of paired tumor and non-tumor liver samples from HCC patients, an immunosuppressive gradient has been described with increased expression of chemokine networks such as CXCR3/CXCL10 and CCR6/CCL20 which enhances macrophage and Treg recruitment to the liver." (PMID 31627733, 2019). "However, as circulating CXCL10 and CXCL9 levels did not correlate with tumor lymphocyte counts, their analysis from the blood samples cannot be used as a biomarker for T-cell rich tumors, further highlighting the importance of analyzing cytokines in primary tumor samples." (PMID 35927313, 2022). "Finally, we show that CXCR3A and CXCL10 are highly expressed in non-metastatic PTC and in the PTC epithelial cell line TPC-1, consistent with a condition that may favor neoplastic transformation and tumor growth." (PMID 29416784, 2018).